ORC4 (origin recognition complex subunit 4)
Description:
Component of the origin recognition complex (ORC) that binds origins of replication. DNA-binding is ATP-dependent. The specific DNA sequences that define origins of replication have not been identified yet. ORC is required to assemble the pre-replication complex necessary to initiate DNA replication. Binds histone H3 and H4 trimethylation marks H3K9me3, H3K27me3 and H4K20me3.
Synonyms: ORC4L; HsORC4; Orc4p
Tractability: Small molecule: a structure with a bound ligand is known. PROTAC: ubiquitination databases record sites on it; its protein half-life has been measured.
Gene: Protein-coding gene on chromosome 2 (147,930,396 to 148,021,784, reverse strand). Ensembl gene ENSG00000115947.
Subcellular location: Nucleus
Subcellular location (Human Protein Atlas): Nucleoli; Nucleoplasm
Pathways (Reactome):
DNA Replication: Activation of the pre-replicative complex; Assembly of the ORC complex at the origin of replication; Assembly of the pre-replicative complex; CDC6 association with the ORC:origin complex; Orc1 removal from chromatin
Cell Cycle: Activation of ATR in response to replication stress; E2F-enabled inhibition of pre-replication complex formation
Gene Ontology:
Molecular function: DNA replication origin binding; nucleotide binding; protein binding; protein-macromolecule adaptor activity; DNA binding
Biological process: DNA replication initiation; DNA replication; polar body extrusion after meiotic divisions; protein polymerization
Cellular component: chromosome, telomeric region; nuclear origin of replication recognition complex; nucleolus; nucleoplasm; nucleus; origin recognition complex; cytoplasm
Genetic constraint (gnomAD): Loss-of-function variants: 7 observed, 8.45 expected, observed/expected ratio (o/e) 0.83, 90% interval 0.47 to 1.53. That is too few expected variants to judge how well the gene tolerates losing a copy. Missense variants: 71 observed, 78.21 expected, observed/expected ratio (o/e) 0.91, 90% interval 0.75 to 1.11. Synonymous variants: 22 observed, 27.74 expected, observed/expected ratio (o/e) 0.79, 90% interval 0.57 to 1.13.
Gene-disease validity (ClinGen):
ClinGen rates the evidence that ORC4 causes each of these diseases.
Meier-Gorlin syndrome 2 (autosomal recessive): Moderate.
Homologues: Orthologues: chimpanzee ORC4 (99% identical), macaque ORC4 (99% identical), pig ORC4 (94% identical), rabbit ORC4 (94% identical), dog ORC4 (92% identical), guinea pig ORC4 (89% identical), mouse Orc4 (89% identical), rat Orc4 (89% identical), tropical clawed frog orc4 (72% identical), zebrafish orc4 (66% identical), Drosophila melanogaster Orc4 (45% identical).
Diseases named in the same sentence as ORC4 in open-access papers:
ORC4 is named in the same sentence as 18 diseases in open-access papers, as found by Europe PMC text mining. Sharing a sentence is not in itself a finding about the gene and the disease. The quoted sentences say what the papers report.
Meier-Gorlin syndrome (9 papers, 2012 to 2022). "Interestingly, although there is no known data on the phenotypic effect of mutating the equivalent residue in human Orc4 (Arg205), mutation of the analogous residue in Orc1 (Arg666, to Trp) has been linked to Meier-Gorlin syndrome." (PMID 34036936, 2021). "In an attempt to uncover the link between potential chromosome replication defects and the phenotypes that characterize Meier-Gorlin syndrome we sought to identify the cellular and molecular defects conferred by the ORC4-MGS mutation (orc4Y232C) using yeast as a model system." (PMID 29036220, 2017). "ORC4 is a causative gene of a subtype of Meier-Gorlin syndrome (MGS), a rare autosomal recessive disorder characterized by severe intrauterine and postnatal growth retardation, developmental delay, microcephaly, bilateral microtia, and aplasia or hypoplasia of the patellae." (PMID 24885232, 2014). "A form of dwarfism known as Meier-Gorlin syndrome (MGS) is caused by recessive mutations in one of six different genes (ORC1, ORC4, ORC6, CDC6, CDT1, and MCM5)." (PMID 29036220, 2017). "Recently, mutations in genes encoding ORC1, ORC4, ORC6, CDT1, and CDC6 were identified in patients displaying Seckel syndrome (SS) and/or Meier-Gorlin syndrome (MGS)." (PMID 23516378, 2013). "Mutations in ORC1, ORC4, ORC6, CDT1, and CDC6, which encode proteins required for DNA replication origin licensing, cause Meier-Gorlin syndrome (MGS), a disorder conferring microcephaly, primordial dwarfism, underdeveloped ears, and skeletal abnormalities." (PMID 23516378, 2013). "Additionally, mutations in key components involved in initiation of DNA replication, such as ORC1, ORC4, ORC6, CDT1, CDT6, and CDC45, have been reported to be the cause of Meier-Gorlin syndrome, a primordial dwarfism syndrome." (PMID 28915237, 2017). "Meier-Gorlin syndrome (MGS) is caused by mutations in components of the prereplication and pre-initiation DNA replication complexes (ORC1, ORC4, ORC6, CDT1, CDC6, GMNN, CDC45), which license replication origins and mediate loading and functioning of the replication fork helicase." (PMID 28630177, 2017).
microcephaly (3 papers, 2013 to 2015). A congenital or acquired developmental disorder in which the circumference of the head is smaller than normal for the person's age and sex. "Mutations in ORC1 and ORC4 appear to cause a more severe short stature and microcephaly than mutations in other genes." (PMID 26381604, 2015). "Patients with ORC1 and ORC4 mutations appear to have the most severe short stature and microcephaly." (PMID 26381604, 2015). "In patients with a severe short stature and/or microcephaly, starting with the analysis of ORC1 and ORC4 should be considered, since mutations in these two genes are associated with a significantly shorter stature and smaller head circumference than mutations in the other genes." (PMID 26381604, 2015).
ciliopathy (1 paper, 2021). A genetic disorder of the cellular cilia or the cilia anchoring structures, the basal bodies, or of ciliary function. "An intriguing connection between MGS and ciliopathy is based on the observation that depletion of ORC1, ORC4, ORC6, CDT1 and CDC6 leads to reduced primary cilia formation." (PMID 33477564, 2021). "When fibroblasts were depleted for ORC1, ORC4, ORC6, CDT1 and CDC6, primary cilia formation was impaired, suggesting that MGS symptoms might constitute a ciliopathy." (PMID 33477564, 2021).
lung carcinoma (1 paper, 2023). "The lung cancer dataset showed that the DNA alteration percentages of the ORC complex were 1.9% (ORC1), 1.7% (ORC2), 1.5% (ORC3), 1.2% (ORC4), 2.2% (ORC5), and 1.4% (ORC6)." (PMID 36205357, 2023).
mastitis (1 paper, 2022). Inflammation of breast tissue during lactation or postpartum due to an obstructed duct or infection. "In this study, the increased gene expression of ORC1, ORC2, ORC4, MCM3, MCM5, and MCM6 in the neutrophils of cows with high SCCs indicated that the cell cycle may be activated in neutrophils in high mastitis risk cows during the transition period." (PMID 35572521, 2022).
cancer (3 papers, 2018 to 2023). A tumor composed of atypical neoplastic, often pleomorphic cells that invade other tissues. "Also overexpressed are three members of the origin recognition complex (ORC4, ORC5, ORC6) that were also previously linked to cancer development." (PMID 29416781, 2018). "Our results indicated that the expression of ORC1, ORC2, ORC3, ORC4, ORC5, and ORC6 was different in the seven common types of tumor‐infiltrating immune cells, such as B cells, CD4 T cells, CD8 T cells, NK cells, macrophages, endothelial cells, and cancer‐associated fibroblasts." (PMID 36205357, 2023).
tumor (2 papers, 2020 to 2023). "Our study revealed that ORC4 expression, highly expressed in tumor tissue, was associated with OS and might be a candidate biomarker for HCC." (PMID 32194798, 2020). "ORC1 and ORC4 expression was significantly correlated with tumor node metastasis (TNM) stage, lymph node metastasis, and recurrence." (PMID 36205357, 2023).
ORC4 also shares sentences with these, for which no sentence is quoted: primordial dwarfism (3 papers); Cirrhosis (1); developmental delays (1); dwarfism (1); genetic disorders (1); intellectual disabilities (1); intrahepatic cholangiocarcinoma (1); liver disease (1); microtia (1); Seizure (1); Werner syndrome (1).